LIG4 (DNA ligase 4)
Diseases named in the same sentence as LIG4 in open-access papers (continued):
Sharing a sentence is not in itself a finding about the gene and the disease.
Fanconi anemia (10 papers, 2007 to 2025). Fanconi anemia (FA) is a hereditary DNA repair disorder characterized by progressive pancytopenia with bone marrow failure, variable congenital malformations and predisposition to develop hematological or solid tumors. "LIG4-deficient patients share features with the genetic instability syndrome Fanconi anemia (FA), including growth failure, bone marrow failure and increased risk of leukemia." (PMID 17224058, 2007). "Indeed, tumors and cytopenia observed in some XRCC4 patients also remind cancer susceptibility in LIG4 deficiency, Fanconi anemia [MIM:PS227650], Ataxia-Teleangiectasia [MIM#208900], and more broadly, genomic instability syndromes such as Mosaic Variegated Aneuploidy [PS257300]." (PMID 40114033, 2025). "We recommend that LIG4 is added to the extensive list of genes to be tested when a diagnosis of Fanconi anaemia is considered as part of the differential diagnosis." (PMID 32534991, 2020). "The assay has successfully identified patients with known mutations in ATM, NBS1, fanconi anemia complementation group A (FANCA), DNA ligase 4 (LIG4) and others." (PMID 29077012, 2017). "In analogy to the bone marrow failure syndromes Fanconi anemia and Dyskeratosis congenita which are characterized by instability of chromosomes or telomeres, genetic instability due to LIG4 deficiency might explain increased radiosensitivity and bone marrow failure in LIG4-deficient patients." (PMID 17224058, 2007). "Likewise, radial/thumb anomalies observed in P2 are also reminiscent of Fanconi anaemia [MIM:PS227650] and ATR-related Seckel syndrome [MIM#210600], more rarely observed in LIG4-related MPD, Nijmegen and Bloom syndromes." (PMID 40114033, 2025).
ovarian carcinoma (10 papers, 2009 to 2025). A malignant neoplasm originating from the surface ovarian epithelium. "Previous studies suggested that XRCC3 rs861539, XRCC2 rs718282, XRCC2 rs3218536, BRCA1 rs1799950, RAD51 rs1801320 and LIG4 rs10131 were associated with the risk of ovarian cancer." (PMID 38890669, 2024). "Previous studies have shown that LIG4 gene polymorphisms are associated with many clinical features of lung and ovarian cancer, such as treatment outcome, progression-free survival, and overall survival." (PMID 36312587, 2022). "There was a 21% increased risk of ovarian cancer associated with the rs1805386 variant in LIG4 among heterozygous carriers and a 34% increased risk among homozygous carriers (P=0.013 and P=0.15, respectively) in the original data." (PMID 19127255, 2009). "LIG4 variants may result in dysfunctional NHEJ and single nucleotide polymorphisms in LIG4 may be associated with an increased risk of developing ovarian cancer." (PMID 34373746, 2021). "Given the key roles played by LIG1, LIG3 and LIG4 in genomic integrity 8 and the response of cancer cells to therapy, we investigated their role in ovarian cancer pathology and potential as novel therapeutic targets." (PMID 34373746, 2021). "This is the first comprehensive study of LIG1, LIG3 and LIG4 in epithelial ovarian cancers." (PMID 34373746, 2021). "Whether LIG1, LIG3 and LIG4 can influence ovarian cancer pathogenesis and therapeutics is largely unknown." (PMID 34373746, 2021). "In this study, we reveal that lactate enhances NHEJ-mediated DNA repair and confers chemoresistance in ovarian cancer by directly facilitating the interaction between XRCC4 and LIG4, the key event in NHEJ machinery assembly." (PMID 41462961, 2025). "LIG1, LIG3 and LIG4 expression profiling in epithelial ovarian cancers: We initially evaluated LIG1, LIG3 and LIG4 expression at protein and transcriptional level in clinical cohorts of epithelial ovarian cancers." (PMID 34373746, 2021). "Indeed, the reciprocal immunoprecipitation of XRCC4 and LIG4 confirm that lactate markedly enhanced the interaction between XRCC4 and LIG4, with lactate treatment strongly promoting the interaction, and LDHi treatment markedly suppressing the interaction, respectively, in ovarian cancer cells." (PMID 41462961, 2025).
ataxia telangiectasia (9 papers, 2007 to 2025). Ataxia-telangiectasia is the association of severe combined immunodeficiency (affecting mainly the humoral immune response) with progressive cerebellar ataxia. "Cellular radiosensitivity in the absence of clinical manifestations of Ataxia telangiectasia lead to the diagnosis of DNA ligase IV (LIG4) deficiency syndrome, confirmed by compound heterozygous mutations in the LIG4 gene." (PMID 17224058, 2007).
bone marrow failure (7 papers, 2007 to 2025). "Lig4 is thought to be significant in DDR because patients with Lig4 syndrome are more susceptible to radiation, as well as more likely to experience neurological problems, bone marrow failure, and malignancy." (PMID 37808268, 2023).
prostate carcinoma (7 papers, 2008 to 2022). A carcinoma that arises from epithelial cells of the prostate gland. "High LIG4 expression was found to be tightly linked to advanced Gleason score, positive nodal involvement, and aggressiveness in prostate cancer." (PMID 28684677, 2017). "High LIG4 expression was found in prostate tumors harboring the TMPRSS2:ERG fusion, a common translocation found in prostate cancers." (PMID 28684677, 2017).
leukemia (6 papers, 2007 to 2023). A malignant (clonal) hematologic disorder, involving hematopoietic stem cells and characterized by the presence of primitive or atypical myeloid or lymphoid cells in the bone marrow and the blood. "Defects in LIG4 could lead to pronounced radio-sensitivity and confer a predisposition to leukemia." (PMID 35003222, 2021). "This hypothesis is supported by the results showing that PARP inhibitors were selectively toxic to LIG4-deficient melanoma and leukemia cells (this work) and that they increased DNA damage induced by radiation exposure in LIG4−/− HCT116 colon carcinoma cell line." (PMID 27705909, 2016). "Currently, clinical trials of selective DNA-PKi are followed by M3814 (also known as Nedisertib and Peposertib) for treating adult solid tumours and leukaemia in combination with or without other therapies, whereas a selective LIG4 inhibitor is not currently available." (PMID 37240360, 2023).
neuroblastoma (6 papers, 2010 to 2023). Neuroblastoma (NB) is the most common solid, extracranial childhood tumor. "Previous studies have indicated that downregulation of LIG4, a gene-encoding LIG4, has been observed in high-risk neuroblastomas derived from patients." (PMID 37763083, 2023). "The expression levels of MYCN and most of the components of NHEJ exhibited a positive correlation, whereas only LIG4 expression had a significant inverse relationship with MYCN expression in the 88 neuroblastoma dataset (Versteeg-88-MAS5.0-u133p2)." (PMID 37240360, 2023). "In sharp contrast to the effect on neuroblastoma spheroids, CHK1i was highly toxic in both LIG4-ablated IMR32 cells and the control cells at comparable levels." (PMID 37240360, 2023). "Collectively, these results indicated the therapeutic implications of LIG4 inhibition in combination with DNA-PKi for MYCN-amplified neuroblastomas." (PMID 37240360, 2023). "Notably, LIG4 was identified as one of the worst prognostic factors in patients with MYCN-amplified neuroblastomas." (PMID 37240360, 2023). "However, further in vitro experiments revealed that LIG4, the worse prognostic factors in MYCN-amplified neuroblastomas, might play complementary roles in DNA-PKcs deficiency." (PMID 37240360, 2023). "As LIG4 acts as part of mainstream NHEJ, we investigated the possible implication of insensitivity to DNA-PKi in MYCN-amplified neuroblastomas." (PMID 37240360, 2023). "Consistently, along with Ku70 and Ku80, other key components of the NHEJ complex, namely DNA ligase 4 and XRCC4, were recovered with MILIP in neuroblastoma cells." (PMID 36445966, 2022). "Collectively, we presume that MYCN-mediated neuroblastoma cell proliferation may largely depend on DNA-PKcs in coordination with ATM; however, if the activation of DNA-PKcs is impaired, LIG4 could complement their repair ability." (PMID 37240360, 2023).
colon carcinoma (5 papers, 2016 to 2023). "In another study, quantitative RT–PCR in 61 paired normal colon and 393 CRCs demonstrated LIG4 downregulation in colon cancer tissues, which was further associated with its promoter hypermethylation." (PMID 33195430, 2020). "This analysis revealed upregulation of XRCC5, PRKDC, and PAXX in colon cancer compared to normal colon tissues, while LIG4 and NHEJ1 (XLF) displayed downregulation." (PMID 33195430, 2020). "While our results also suggest consistent downregulation of LIG4 mRNA expression in tumor cells, proteomic analysis displayed higher LIG4 levels in colon tumors." (PMID 33195430, 2020). "To determine the expression pattern of core NHEJ genes in colon cancer, we performed Oncomine analysis for XRCC6 (Ku70), XRCC5 (Ku80), PRKDC (DNA-PKcs), XRCC4 (XRCC4), LIG4 (DNA ligase 4), NHEJ1 (XLF), and PAXX (PAXX/XLS)." (PMID 33195430, 2020). "Our analysis revealed that BRAF mutant colon cancer did not harbor higher NHEJ1 expression compared to BRAF wild type tumors and three NHEJ pathway genes, XRCC5, PRKDC, and LIG4 are indeed lowly expressed in BRAF mutant tumors." (PMID 33195430, 2020).
Dubowitz syndrome (5 papers, 2007 to 2022). A rare multiple congenital syndrome characterized primarily by growth retardation, microcephaly, distinctive facial dysmorphism, cutaneous eczema, a mild to severe intellectual deficit and genital abnormalities. "Short telomeres are a diagnostic criterion for DC, but can also be found in other DNA repair deficiencies including LIG4 deficiency and Dubowitz syndrome." (PMID 34716846, 2022). "The diagnosis of Dubowitz syndrome has been considered in other patients later determined to have LIG4 mutations." (PMID 24892279, 2014). "Lastly Yue found compound heterozygous mutations in the nuclear ligase gene LIG4 in the sister from a pair of siblings previously reported with Dubowitz syndrome who are also investigated in this report (Patient 2)." (PMID 24892279, 2014). "In summary, we report three patients originally diagnosed with the Dubowitz syndrome but who were instead determined to have LIG4 mutations (Patients 1 and 2) or a deletion at chromosome 17q24.2–24.3 (Patient 3)." (PMID 24892279, 2014). "The knowledge that LIG4 mutation is responsible for the disease should have significant clinical impact for the care of similar Dubowitz syndrome patients." (PMID 23372718, 2013). "Thus, we have identified the genetic defects in this case of Dubowitz syndrome as compound mutations of 613ΔT (L205FS) and 2440C>T (R814X) of the human LIG4 gene." (PMID 23372718, 2013).
lung carcinoma (5 papers, 2013 to 2020). "In the present study, the primary objectives were to investigate the incidence of RP of lung cancer patients after the treatment of radiotherapy and to analyze the association between the LIG4 and HSPB1 genes polymorphisms and RILI in lung cancer patients." (PMID 25811031, 2015). "Therefore, the SNP of LIG4 may be associated with the increased risk of lung cancer and may be served as a very important marker in relation to the susceptibility to clinical radiosensitivity and RILI." (PMID 25811031, 2015). "The present study is conducted to investigate whether the genetic polymorphisms of LIG4 and HSPB1 are involved in the increased risk of RILI among patients with lung cancer after radiotherapy." (PMID 25811031, 2015). "Nevertheless, we found that the LIG4 genetic polymorphisms (rs1805388 C>T) were not significantly connected with the RILI in lung cancer patients." (PMID 25811031, 2015).
lymphoma (5 papers, 2007 to 2025). A malignant (clonal) proliferation of B- lymphocytes or T- lymphocytes which involves the lymph nodes, bone marrow and/or extranodal sites. "Hematopoietic cancers accounted for 23.9% of cases in patients with LIG4 deficiency, particularly lymphomas (both EBV-positive and EBV-negative), lymphoid leukemias, and MDS." (PMID 40047910, 2025). "Here, we describe five cases of DNA Ligase 4 deficiency (MIM phenotype number #606593) in two unrelated families from Mexico, whose clinical presentations ranged from lymphoma and early death, to mild disease." (PMID 30719430, 2018).
melanoma (5 papers, 2010 to 2023). A malignant, usually aggressive tumor composed of atypical, neoplastic melanocytes. "In concordance, we demonstrated that LIG4 deficient melanoma cells were highly sensitive to the combination of an alkylating agent dacarbazine and PARPi." (PMID 30627327, 2018). "PARP1 inhibition caused accumulation of DSBs, which was associated with apoptosis in LIG4 deficient melanoma cells." (PMID 27705909, 2016). "In summary, PARP1 inhibitor seems to offer additional treatment opportunity to pre-selected melanomas displaying LIG4 (and/or XRCC4) deficiency." (PMID 27705909, 2016). "This work for the first time demonstrates the effectiveness of a combination of PARP1 inhibitor olaparib and alkylating agent DTIC for treating LIG4 deficient melanomas." (PMID 27705909, 2016). "In addition, olaparib combined with DTIC inhibited the growth of LIG4 deficient human melanoma xenografts." (PMID 27705909, 2016). "Our hypothesis that olaparib is synthetic lethal with LIG4 deficiency in melanoma cells was supported by selective anti-tumor effects of olaparib used either alone or in combination with dacarbazine (DTIC) in LIG4 deficient, but not LIG4 proficient cells." (PMID 27705909, 2016). "We observed that PARP1 inhibitor olaparib sensitized melanomas with reduced expression of DNA ligase 4 (LIG4) to an alkylatimg agent dacarbazine (DTIC) treatment in vitro, while normal melanocytes remained intact." (PMID 27705909, 2016). "Our work for the first time demonstrates that downregulation of LIG4 in melanoma cells is directly responsible for enhanced sensitivity to olaparib." (PMID 27705909, 2016). "Our results suggest the new therapeutic approach against melanomas based on synthetic lethality which exploits the reduced levels of LIG4, an essential component of D-NHEJ that performs the final ‘end processing' step of DSB repair." (PMID 27705909, 2016). "In particular, all melanoma lines showed a decreased level of DNA ligase 4 (LIG4)." (PMID 27705909, 2016). "Moreover, transcriptome analysis by microarrays of 229 melanoma cell lines detected downregulation of at least one member of D-NHEJ pathway (including LIG4) in numerous samples established from patients manifesting different stages of malignancy." (PMID 27705909, 2016). "Supporting this hypothesis, we have demonstrated that melanoma cells lacking LIG4 were highly susceptible to a combination of the alkylating agent dacarbazine and PARPi." (PMID 37763083, 2023). "Protein expression status of LIG4, RAD51, PARP1, Ku70 was determined by Western blot analysis in normal melanocytes and melanoma cell lines (DMBC11, DMBC12)." (PMID 27705909, 2016). "In the present study we showed that PARP1 inhibitor olaparib applied alone and in combination with DTIC (a drug used in melanoma treatment) was effective against melanoma cells displaying downregulation of LIG4 without affecting normal melanocytes." (PMID 27705909, 2016).
multiple myeloma (5 papers, 2007 to 2022). "Decreases in XRCC4 and DNA Lig3 and Lig4 are associated with a decline in NHEJ efficiency and fidelity, and impaired NEHJ has been reported after irradiation in previous studies using myeloma cell lines." (PMID 36420194, 2022).
Cernunnos-XLF deficiency (4 papers, 2012 to 2025). Cernunnos-XLF deficiency is a rare form of combined immunodeficiency characterized by microcephaly, growth retardation, and T and B cell lymphopenia. "Consistent with our findings, a study involving patients with DSBR identified 77 individuals affected by LIG4 deficiency, Cernunnos deficiency, or NBS." (PMID 40047910, 2025). "In the large international series of patients transplanted for DNA ligase 4 deficiency, cernunnos-XLF deficiency and NBS there were no reported cases of lymphoma development, or the development of secondary malignancies in 212 patient follow up years." (PMID 35454905, 2022).
diabetes (4 papers, 2014 to 2023).
medulloblastoma (4 papers, 2013 to 2018). A malignant, invasive embryonal neoplasm arising from the cerebellum.
Omenn syndrome (4 papers, 2018 to 2023). An inflammatory condition characterized by erythroderma, desquamation, alopecia, chronic diarrhea, failure to thrive, lymphadenopathy, and hepatosplenomegaly, associated with severe combined immunodeficiency (SCID). "Multiple genes presenting as Omenn syndrome, such as RAG1/2, ADA, LIG4, ZAP70, etc." (PMID 37755421, 2023).
primary immunodeficiency (4 papers, 2016 to 2023). "DNA ligase IV (LIG4) deficiency is an extremely rare autosomal recessive primary immunodeficiency disease caused by mutations in LIG4." (PMID 34630384, 2021). "Lig4 deficiency causes a rare primary immunodeficiency known as Lig4 syndrome." (PMID 37808268, 2023).
primordial dwarfism (4 papers, 2014 to 2021). "even screened some LIG4 deficiency patients for microcephalic primordial dwarfism before making a diagnosis of CID or SCID." (PMID 34630384, 2021). "Here, we report the identification of biallelic truncating LIG4 mutations in 11 patients with microcephalic primordial dwarfism presenting with restricted prenatal growth and extreme postnatal global growth failure (average OFC −10.1 s.d., height −5.1 s.d.)." (PMID 24123394, 2014).
Seckel syndrome (4 papers, 2014 to 2025). A rare autosomal recessive inherited syndrome caused by mutations in the ATR gene, RBBP8 gene, CENPJ gene, CEP152 gene, CEP63 gene, NIN gene, DNA2 gene, or TRAIP gene. "“Bird-like” or “Seckel syndrome-like” traits are always observed in LIG4 deficiency patients." (PMID 34630384, 2021).
viral infection (4 papers, 2012 to 2023). "Some cytoplasmic forms of LIG4 have been reported in response to specific viral infections and the LIG4 protein has been shown to regulate the nuclear localization of XRCC4, suggesting that XRCC4 may potentially interact with ATM in the cytoplasm in the case of specific mutations of LIG4." (PMID 36551628, 2022).
acute myeloid leukemia (3 papers, 2020 to 2025). Acute myeloid leukemia (AML) is a group of neoplasms arising from precursor cells committed to the myeloid cell-line differentiation. "Expression of Lig4 is especially high in B- and T-ALL when compared to other childhood cancers, whereas acute myeloid leukemia (AML) samples expressed the lowest levels of Lig4." (PMID 39866872, 2025).